PCBD1 (pterin-4 alpha-carbinolamine dehydratase 1)
Description:
Involved in tetrahydrobiopterin biosynthesis (By similarity). Seems to both prevent the formation of 7-pterins and accelerate the formation of quinonoid-BH2. Coactivator for HNF1A-dependent transcription (By similarity). Regulates the dimerization of homeodomain protein HNF1A and enhances its transcriptional activity (By similarity). Also acts as a coactivator for HNF1B-dependent transcription.
Synonyms: PHS; DCoH; PCD; PCBD
Tractability: PROTAC: ubiquitination databases record sites on it; its protein half-life has been measured.
Gene: Protein-coding gene on chromosome 10 (70,882,280 to 70,888,605, reverse strand). Ensembl gene ENSG00000166228.
Subcellular location: Cytoplasm; Nucleus
Subcellular location (Human Protein Atlas): Nucleoplasm; Cytosol
Pathways (Reactome):
Metabolism: Phenylalanine metabolism
Gene Ontology:
Molecular function: identical protein binding; protein binding; 4-alpha-hydroxytetrahydrobiopterin dehydratase activity; transcription coactivator activity; phenylalanine 4-monooxygenase activity
Biological process: L-tyrosine biosynthetic process; positive regulation of DNA-templated transcription; tetrahydrobiopterin biosynthetic process
Cellular component: cytoplasm; cytosol; extracellular exosome; nucleoplasm; nucleus
Genetic constraint (gnomAD): Loss-of-function variants: 13 observed, 12 expected, observed/expected ratio (o/e) 1.08, 90% interval 0.7 to 1.68. The upper end of that interval is the gene's LOEUF score, 1.68, which puts it in group 6 of 6, group 1 being the genes least tolerant of losing a copy. Missense variants: 86 observed, 137.15 expected, observed/expected ratio (o/e) 0.63, 90% interval 0.53 to 0.75. Synonymous variants: 53 observed, 52.83 expected, observed/expected ratio (o/e) 1, 90% interval 0.8 to 1.26.
Gene-disease validity (ClinGen):
ClinGen rates the evidence that PCBD1 causes each of these diseases.
pterin-4 alpha-carbinolamine dehydratase 1 deficiency (autosomal recessive): Definitive.
Homologues: Orthologues: chimpanzee PCBD1 (100% identical), guinea pig PCBD1 (100% identical), macaque PCBD1 (100% identical), pig PCBD1 (100% identical), dog PCBD1 (99% identical), mouse Pcbd1 (99% identical), rat Pcbd1 (99% identical), tropical clawed frog pcbd1 (87% identical), rabbit PCBD1 (76% identical), zebrafish pcbd1 (70% identical), Caenorhabditis elegans pcbd-1 (62% identical), Drosophila melanogaster Pcd (56% identical). Paralogues in human: PCBD2 (61% identical).
Diseases named in the same sentence as PCBD1 in open-access papers:
PCBD1 is named in the same sentence as 27 diseases in open-access papers, as found by Europe PMC text mining. Sharing a sentence is not in itself a finding about the gene and the disease. The quoted sentences say what the papers report.
diabetes (8 papers, 2016 to 2024). "More studies are warranted to further investigate the pathogenetic mechanisms of PCBD1, the associated diabetes clinical course, and the response to treatment." (PMID 39201476, 2024). "Finally, molecular work to identify new genes involved in diabetes showed hyperphenylalaninemia on newborn screening in patients with PCBD1 mutations, demonstrating how multiple metabolic networks can influence diabetes development." (PMID 33076340, 2020). "Our studies also highlighted significant eTWAS for T2D, including PCBD1, which is mutated in a syndrome that includes monogenic diabetes, and encodes a co-factor of HNF1A, an established monogenic diabetes gene." (PMID 36109769, 2022). "However, mutations in PCBD1 are associated with both hypomagnesaemia and risk for HNF1A-like Maturity Onset Diabetes of the Young (MODY3) diabetes in puberty, so patients with PCBD1 mutations should be screened for these disorders." (PMID 32456656, 2020). "Thus, in order to optimize the clinical management in this subset of patients, screening for biallelic mutations in PCBD1 has been suggested in the case of HNF1A-like diabetes occurrence with absent alterations in HNF1A and HNF1B." (PMID 39201476, 2024). "Pterin-4-alpha-carbinolamine dehydratase (PCBD1) is a novel protein that acts as a cofactor for HNF1A-dependent transcription protein, and it is reported that PCBD1 mutations cause early-onset nonautoimmune diabetes with features similar to dominantly inherited HNF1A-diabetes." (PMID 26901059, 2016). "A previous investigation presented genetic proof that mutations in PCBD1 can lead to the development of early-onset nonautoimmune diabetes, which exhibits characteristics resembling dominantly inherited HNF1A-diabetes." (PMID 38660376, 2024).
Hyperphenylalaninemia (4 papers, 2022 to 2025). "WES analysis has shown that neither of these patients had pathogenic, likely pathogenic, or variants of uncertain significance (VUS) above 50% posterior probability in genes associated with hyperphenylalaninemia (GCH1, PCBD1, PTS, QDPR, SPR and DNAJC12)." (PMID 40473815, 2025). "When no PAH variants are detected in a child with hyperphenylalaninemia, the genes for the various tetrahydropterin BH4 deficiencies are tested, such as GCH1, PTS, QDPR, and PCBD1." (PMID 38132826, 2023).
Hypomagnesemia (4 papers, 2017 to 2022). An abnormally decreased magnesium concentration in the blood. "Patients with dominant mutations in the hepatocyte nuclear factor 1B (HNF1B) gene or recessive mutations in the pterin-4 alpha-carbinolamine dehydratase 1 (PCBD1) gene can develop hypomagnesemia and maturity-onset diabetes of the young." (PMID 30889804, 2019). "Mutations in FXYD2 (G41R), and transcription factors (HNF‐1B and PCBD1) that affect FXYD2 expression are associated with hypomagnesemia with hypermagnesuria." (PMID 30175537, 2018). "Due to the dual activity of the coded product of PCBD1, this BH4D has been related to early-onset nonautoimmune (MODY)-type diabetes and hypomagnesemia due to renal magnesium wasting." (PMID 36313470, 2022).
maturity-onset diabetes (2 papers, 2019 to 2024). "Compared with all cell types, beta cells had the most genes with time–glucose interaction effects, featuring several well-established type 2 diabetes genes, including INS, ABCC8, SLC30A8 and PCBD1." (PMID 38967666, 2024).
DHPR deficiency (1 paper, 2023). "Patients were diagnosed as follows: nine patients affected by PTPS deficiency (and identified PTS variants), two patients affected by Pterin‐four alpha‐carbinolamine dehydratase deficiency (and identified PCBD1 variants) and one patient affected by DHPR deficiency (and identified QDPR variants)." (PMID 36537053, 2023).
dysplasia (1 paper, 2025). A usually neoplastic transformation of the cell, associated with altered architectural tissue patterns. "When we examined differential gene expression across these clonal populations, we identified a distinct transcriptional signature in the dysplasia origin clone, with several genes including TPM2, FAU, PCBD1, and APCDD1 showing consistent upregulation." (PMID 41360789, 2025).
phenylketonuria (1 paper, 2014). Phenylketonuria (PKU) is the most common inborn error of amino acid metabolism and is characterized by mild to severe mental disability in untreated patients. "To develop a rapid method for the diagnosis of phenylketonuria (PKU) and tetrahydrobiopterin (BH4) deficiency, we designed a multiplex, PCR-based primer panel to amplify all the exons and flanking regions (50 bp average) of six PKU-associated genes (PAH, PTS, GCH1, QDPR, PCBD1 and GFRP)." (PMID 24705691, 2014).
renal cell carcinoma (1 paper, 2025). "It was shown that renal cell carcinoma (RCC) patients’ urine EVs included lower levels of mRNA for pterin-4 alpha-carbinolamine dehydratase-1 (PCBD1), glutathione transferase alpha 1 (GSTA1), and CCAAT enhancer binding protein alpha (CEBPA) than controls." (PMID 40305328, 2025).
PCBD1 also shares sentences with these, for which no sentence is quoted: cancer (2 papers); colorectal cancer (2); Bartter syndrome type 3 (1); Bartter syndrome type 4 (1); EAST syndrome (1); Fever (1); genetic disorders (1); Gitelman syndrome (1); infection (1); Intellectual disability (1); kidney cancer (1); lung carcinoma (1); major depressive disorder (1); metabolic disorder (1); MODY (1); movement disorder (1); Myeloma (1); posttraumatic stress disorder (1); sarcoma (1).